MMP16 (matrix metallopeptidase 16)
Diseases named in the same sentence as MMP16 in open-access papers (continued):
Sharing a sentence is not in itself a finding about the gene and the disease.
cancer (continued). "As anticipated, the MMP16 mRNA expression levels in cancer tissues were significantly higher than their paired adjacent normal mucosa (P < 0.001)." (PMID 29069779, 2017). "We then studied MMP16 expression in 25 paired cases cancer tissues and their adjacent normal tissues by RT-PCR and IHC study." (PMID 29069779, 2017). "The frequent upregulation of MMP16 expression in human GC highlights its potential as a novel therapeutic target for this cancer." (PMID 27340864, 2016). "MMP16 gene is a key biomarker of cancer that plays a role in the invasive behavior of cancer cells." (PMID 38560573, 2024). "Degradation of extracellular and microRNAs in cancer is an important pathway related to MMP16." (PMID 34587931, 2021). "Moreover, the expression level of MMP-16, which participates in the occurrence and development of many cancers, was negatively correlated with the miR-328-3p expression in OS cells." (PMID 31043859, 2019). "Interestingly, MT-MMPs (MMP-14 and MMP-16) have been reported to play pivotal roles in cancer cell migration and metastasis." (PMID 29643421, 2018). "We tested whether the MMP16 promoted cancer cell invasion and metastases by way of induction of the EMT process." (PMID 29069779, 2017). "In addition, we found that human MMP16, known to have critical roles in cancer invasion, contained putative conserved miR-328 target site." (PMID 22453125, 2012). "Therefore, MMP16 has been identified as a potential therapeutic target and biomarker of cancer." (PMID 38560573, 2024). "Additionally, following 12h of TGF-β1 treatment, expression levels of miR-200b were reduced gradually, implying that miR-200b is a metastasis-inhibiting miRNA in BLCA, which was confirmed when miR-200b overexpression inhibited TGF-β1 induced MMP-16 upregulation and cancer cell migration." (PMID 33672684, 2021). "Finally, both CRP and FFV PEVs significantly upregulated gene expression of ECM components (e.g. MMP14, MMP16, collagen type V alpha 1 chain, versican) as well as the genes SERPINE1 and PMEPA1, which are associated with epithelial-to-mesenchymal transition in various cancer types." (PMID 39695652, 2024). "MMP16, a new member of the MMP family, has been reported to be upregulated in various cancers compared to normal tissue." (PMID 39073693, 2024). "As a crucial member of the MMP family, MMP16 can also display proteolytic activity against components of the ECM, and MMP16 is highly expressed in many types of human cancers and promotes their progression." (PMID 34747300, 2021). "Since epithelial-mesenchymal transition (EMT) is closely related to cancer cell metastasis ability, we then examined EMT markers in MMP16 knockdown cells and their control cell lines." (PMID 29069779, 2017). "MiR-328 has an important role in maintaining cancer stem-like SP phenotype by directly targets ABCG2 and MMP16." (PMID 22453125, 2012). "IQGAP1 and MMP16 mRNAs level was significantly higher in the cancers than in the NC (p < 0.05), but not AKT mRNA levels." (PMID 39073693, 2024). "Results of this analysis showed a significant increase in MMP2, MMP9, MMP12, and MMP16 levels in KIRC patients across different cancer stages, races, genders, and age groups when compared to normal controls." (PMID 38560573, 2024). "Thus, matrix-degrading proteases, such as MMP-2, MMP-9, MMP-14 (MT1-MMP), and MMP-16 (MT3-MMP), were reported to be required for EMT progression of different cancer types." (PMID 36766694, 2023). "Additionally, the gene targets of these miRNAs included several cancer driver genes including ZNF704 (targeted by ten miRNAs), MMP16 (targeted by eight miRNAs), and KCNN3, POU2F1, ADARB1, MPZL1, RUNX1T1, UBE2W, and DYRK1A genes (targeted by seven miRNAs)." (PMID 37685851, 2023). "Other members of the MMP family (MMP15, MMP16, MMP19, and MMP27) showed no differential expression between pancreatic normal and cancer tissues." (PMID 37821678, 2023).
cancer (continued). "In the present study, changes in the expression of MMP2, MMP9, and MMP16 genes between patients with AML and people without cancer were examined." (PMID 34035811, 2021).
adenocarcinoma (1 paper, 2020). A common cancer characterized by the presence of malignant glandular cells. "MMP-9 and MMP-16 show greater expression with villous histological type versus NOS adenocarcinoma (p = 0.01 and fold change of 1.13 and p = 0.03 and fold change of 1.61)." (PMID 32813775, 2020). "The expressions of MMP-9 and MMP-16 have shown a statistical relationship with the villous histological type in comparison to NOS adenocarcinoma." (PMID 32813775, 2020). "In the present study, there was a statistically significant correlation between the expression of MMP-16 and CRC when greater expression was observed in villous types, which have a better prognosis than the NOS adenocarcinoma type." (PMID 32813775, 2020).
infection (1 paper, 2019). The state of being infected such as from the introduction of a foreign agent such as serum, vaccine, antigenic substance or organism. "gga-miR-146c was functional by regulating TLR6/MyD88/NF-κB pathway and targeting MMP16 to manipulate cell cycle, multiplication, and apoptosis in host defense of MG-HS infection." (PMID 31137698, 2019). "Eight to eleven days after infection (amount 17 to 20 days of egg hatching), MMP16 expression was significantly decreased in MG-infected lungs of chicken embryos." (PMID 31137698, 2019). "It was significant that MMP16 expression level was lower in the infection group." (PMID 31137698, 2019).
metabolic disease (1 paper, 2023). A congenital disorder (due to inherited enzyme abnormality) or acquired (due to failure of a metabolically important organ) disorder resulting from an abnormal metabolic process. "Multiple lines of evidence at the mammalian genome, transcriptome, and phenome levels further supported the evidence for the causality between MMP16 variants and the metabolic diseases, brain development, and cartilage tissues in Chinese pigs." (PMID 38053015, 2023). "To our knowledge, this is the first study to demonstrate the association between MMP16 and its adaptive domestication in Chinese indigenous pigs, and we supposed it may relate to the pain tolerance to metabolic diseases in pigs brought in artificial breeding." (PMID 38053015, 2023).
Muscular Disorders (1 paper, 2022). "From twenty genes of “Cellular Development, Cellular Movement, Skeletal and Muscular Disorders”, six DEGs in the top network related to RSK1 KO (TTLL12, ADMA22, FN1, LPAR1, MMP16, and NRN1) were highly correlated with RSK1 expression, with significant R and p values." (PMID 36684450, 2022).
neurological disorders (1 paper, 2025). "MMP16, located in the second island, is involved in cartilage formation, regeneration, and neurological disorders in Chinese pigs." (PMID 40492600, 2025).
psychiatric diseases (1 paper, 2022). "Our results showed that MMP genes such as MMP-15, MMP-16, MMP-17, MMP-24 and MMP-28 were expressed highly or moderately in brain, implying the values in investigation of more genes in association with psychiatric diseases." (PMID 35444067, 2022).
MMP16 also shares sentences with these, for which no sentence is quoted: endometrial carcinoma (2 papers); esophageal squamous cell carcinoma (2); non-small cell lung carcinoma (2); amyotrophic lateral sclerosis (1); Anxiety (1); atrial fibrillation (1); brain disease (1); brain tumors (1); cerebral cavernous malformation (1); chondrodysplasia (1); colorectal tumors (1); cutaneous squamous cell carcinoma (1); endometriosis (1); esophageal cancer (1); heart failure (1); hyperprolactinemia (1); invasive ductal carcinoma (1); leiomyoma (1); leukemia (1); malignant glioma (1); metastatic melanoma (1); Myocardial fibrosis (1); neurodegenerative disease (1); nodular melanoma (1); ovarian endometriosis (1); skin cancer (1); small cell lung carcinoma (1); uveal melanoma (1); viral hepatitis (1).